FGB (fibrinogen beta chain)
Diseases named in the same sentence as FGB in open-access papers (continued):
Sharing a sentence is not in itself a finding about the gene and the disease.
islet cell tumors (1 paper, 2007). "Consistent with previously published findings, genes with significantly elevated expression in islet cell tumors included insulinoma-associated 1 (INSM1), glutaminyl-peptide cyclotransferase (QPCT), fibrinogen B beta polypeptide (FGB), peroxisomal biogenesis factor 7 (PEX7)." (PMID 17389914, 2007).
liver cirrhosis (1 paper, 2025). "Additionally, another six genes (ALB, APOH, FABP1, FGB, FGG, and TF) were identified from our previous HCC EV-specific gene panel given their performance in distinguishing early-stage HCC from liver cirrhosis." (PMID 40307890, 2025).
lymph node metastasis (1 paper, 2022). "The expression of FGB was associated with TNM stage and lymph node metastasis and showed a positive correlation." (PMID 36438895, 2022).
major depression (1 paper, 2014). "The most interesting finding in this study was higher PDIA3 expression and lower FGB, GPX-1, and RARB expression in patients with major depression than in healthy controls." (PMID 24383611, 2014). "The levels of fibrinogen beta chain (FIBB), fibrinogen gamma chain (FIBG), retinoic acid receptor beta (RARB), glutathione peroxidase 1 (GPX1), SH3 domain-containing protein 19 (SH319), and T-complex protein 1 subunit beta (TCPB) were lower in patients with major depression than in healthy controls." (PMID 24383611, 2014).
malaria (1 paper, 2016). Malaria is a serious and sometimes fatal disease caused by a parasite that commonly infects a certain type of mosquito which feeds on humans. "Again, Fibrinogen beta chain and plasminogen released in the malaria plasma MPs were significantly higher compared to control plasma." (PMID 28352210, 2016).
metastatic colorectal cancer (1 paper, 2022). "Fibrinogen beta chain (FGB), a component of fibrinogen, is a biomarker for hepatic metastatic colorectal cancer." (PMID 36499216, 2022).
nasal polyp (1 paper, 2021). "Coagulation proteins FGA, FGB, FGG, and fibronectin (FN1) were all also abundant in nasal polyp biopsies in this study." (PMID 33220024, 2021).
ovarian serous carcinoma (1 paper, 2013). "Nonetheless, Q-RT-PCR analysis corroborated elevated F2, FGA and FGB transcript levels in a small, independent set of freshly-frozen ovarian CCC (n = 6) compared to ovarian serous carcinomas (n = 7) (P≤0.01, Mann-Whitney U-test)." (PMID 24040285, 2013).
polyp (1 paper, 2019). A usually exophytic mass attached to the underlying tissue by a broad base or a thin stalk. "FGB (Fibrinogen beta chain) represents significant down-regulation changes in both processes; transformation of normal into polyp tissue and polyp into cancerous tissue, however, C4A expression decreased significantly solely in polyp rather than normal tissue." (PMID 31749922, 2019).
psychosis (1 paper, 2024). "C4B, Complement C4-A (C4A), Complement C2 (C2), A2M, LRG1, and the Fibrinogen alpha, beta, and gamma chains (FGA, FGB, and FGG) were differentially expressed between those who transitioned to psychosis and those who did not, adjusting for age, sex, and study." (PMID 38243809, 2024).
renal agenesis (1 paper, 2025). Renal agenesis (RA) is a form of renal tract malformation characterized by the complete absence of development of one or both kidneys (unilateral RA or bilateral RA respectively), accompanied by absent ureter(s). "Eighty‐eight percent of cases were isolated (7/8, 95% CI, 64.6%–110.4%), and one case was associated with structural abnormalities/left sided gallbladder and bilateral renal agenesis (non‐isolated FGB duplication)/." (PMID 39702857, 2025).
renal fibrosis (1 paper, 2022). A final common manifestation of a wide variety of chronic kidney diseases characterized by glomerulosclerosis and tubulointerstitial fibrosis. "Furthermore, hsa_circ_0012138, homologous with circRNA_37492, may potentially target miR-651-5p/FGB axis in human renal fibrosis." (PMID 35246505, 2022). "Interestingly, hsa_circ_0012138/miR-651-5p/FGB may constitute potential ceRNA axis in human renal fibrosis, according to further study." (PMID 35246505, 2022).
salivary gland tumors (1 paper, 2024). "Some of the identified peptides were derived from proteins previously suggested as potential biomarkers of salivary gland tumors (ANXA1, BPIFA2, FGB, GAPDH, HSPB1, IGHG1, VIM) or tumors of other tissues or organs (SERPINA1, APOA2, CSTB, GSTP1, S100A8, S100A9, TPI1)." (PMID 39201484, 2024).
seminoma (1 paper, 2021). A radiosensitive malignant germ cell tumor found in the testis (especially undescended), and extragonadal sites (anterior mediastinum and pineal gland). "Compared with the seminoma / EC cell lines, the aYST cell line GCT72 showed high expression of the proposed YST factors (except AFP and FGB), respectively." (PMID 33448076, 2021).
tubulointerstitial nephritis (1 paper, 2012). "Other proteins detected included collagen VI α-1/α-2 (Col6a1/Col6a2), fibrinogen beta chain (FGB), transglutaminase 2 isoform A (TGM2A), b-actin variant (ACTB), 70 kD heat shock protein 5 (HSPA5), nidogen 2 (NID2), CD49f, βIG-H3, and tubulointerstitial nephritis (TIN)." (PMID 22701492, 2012).
yolk sac tumour (1 paper, 2005). "In addition, we identified a high expression of FGB gene, which may be a new marker for yolk sac tumour component of mixed TGCTs." (PMID 15856041, 2005).
ZIKV infection (1 paper, 2022). "Since the proteins fibrinogen-α (FGA), fibrinogen-β (FGB), and fibrinogen-γ (FGG) are overexpressed, and these are precursors of fibrin, a major component of blood clots, these data indicate that the coagulation cascade is being activated in the placental tissue upon ZIKV infection." (PMID 34264436, 2022).
tumor (16 papers, 2009 to 2025). "On a larger cohort of patients, our study succeeded in confirming this increase in content and strengthening the hypothesis of an association between the accumulation of both FGB and its cleaved products and gastric malignancy directly in tumor tissues." (PMID 29518939, 2018). "We found that tumor cells in the high-complexity group originated from the cell lineage with FGB overexpression and exhibited high levels of transcription factors associated with poor survival." (PMID 39268081, 2024). "Meanwhile, Cebpb silencing consistently reduced TGF-β and FGB production by CD45+EPCs in tumor tissues." (PMID 37649603, 2023). "Herein, we demonstrate that circ_16601 promotes LUAD progression and my-CAF recruitment in the tumor microenvironment by upregulating FGB expression." (PMID 37953225, 2023). "Results showed that knockdown of FGB markedly inhibited the tumor growth, including tumor weight and volume." (PMID 36438895, 2022). "FGB was more highly expressed in BC tumor, and the expression of FGB was relevant to TNM stage and lymph node metastasis and showed a positive correlation." (PMID 36438895, 2022). "In order to figure out the influence of FGB knockdown on tumor growth in vivo, the xenograft tumor model was constructed successfully." (PMID 36438895, 2022). "The present study found that FGB was more highly expressed in BC tumor tissue, and the expression of FGB was relevant to TNM stage and LNM and showed a positive correlation." (PMID 36438895, 2022). "The xenograft tumor model was constructed to figure out the influence of FGB knockdown on tumor growth in vivo." (PMID 36438895, 2022). "HBV integration led to an evident upregulation of TERT, CCNE1, and FGB in the tumor (compared to the adjacent tissue)." (PMID 34642322, 2021). "Our data are thus insufficient to provide a clear information about a correlation between plasma fibrinogen level and FGB spot content in situ in the tumor microenvironment." (PMID 29518939, 2018). "Additionally, overexpression of Cebpb by AAV increased production of TGF-β and FGB by splenic CD45+EPCs in tumor-bearing mice." (PMID 37649603, 2023). "However, overexpression of miR-5580-5p and knockdown of FGB effectively reversed the tumor-promoting effect of circ_16601 in LUAD, as evidenced by measuring tumor weight and volume." (PMID 37953225, 2023). "Increased expression of FGB has been associated with cancer metastasis and poor prognosis in various types of cancers, while YAP1 overexpression has been observed in multiple cancers, promoting tumor growth and metastasis." (PMID 37953225, 2023). "The mRNA expression of FGB was obviously raised in BC tumor tissues." (PMID 36438895, 2022). "In contrast to the sh-NC group, knockdown of FGB markedly decreased tumor weight and volume." (PMID 36438895, 2022). "FGB downregulation markedly inhibited the tumor growth, including tumor weight and volume." (PMID 36438895, 2022). "Higher protein contents of the entire form of FGB (~50 kDa) and isoforms containing plasmin-cleavage product “fragment D” of FGB (~37–40 kDa) were found in tumoral gastric tissues compared with non tumoral adjacent tissues, at both early (Group I: T1–T2) and advanced tumor depth (Group II: T3–T4)." (PMID 29518939, 2018). "Besides, FGB was reported to contribute to tumor angiogenesis and metastasis." (PMID 36969077, 2023). "Fibrinogen beta chain (FGB), filamin-A (FLNA), and fibrinogen gamma chain (FGG) were associated with homotypic cell-cell adhesion and regulation of substrate adhesion-dependent cell spreading, which were closely related to the invasion and metastasis of tumor cells." (PMID 37124724, 2023). "We found that the expression levels of seven integrin ligands (COL4A6, COL13A1, FGB, COL19A1, COL18A1, COL14A1, and COL11A2) were negatively correlated with the Gleason score, suggesting that the suppression of integrins and/or their ligands is associated with more advanced tumor grade." (PMID 19653896, 2009).
tumor (continued). "In contrast, GLYs, such as the fibrinogen family (FGA, FGB, and FGG), fibronectin (FN1), transforming growth factor beta-induced protein (TGFβI), and tenascin-C (TNC), had an increased presence in tumor tissues." (PMID 40032993, 2025). "The fibrinogen subunits FGB and FGG play essential roles in the tumor microenvironment by promoting thrombosis, which has been linked to HCC progression." (PMID 40307890, 2025). "FGB and FGG, components of the extracellular matrix protein fibrinogen, are crucial for wound healing and hemostasis and function in tumor angiogenesis and metastasis." (PMID 37953280, 2023). "In fact, we were able to detect five upregulated proteins in the normal mucosa adjacent to the tumor, namely laminin subunit alpha-4 (LAMA4), elastin microfibril interfacer 1 (EMILIN1), LTBP1 and fibrinogen beta chain (FGB), as well as proteoglycan versican core protein (VCAN)." (PMID 35340765, 2022).
infection (8 papers, 2009 to 2025). The state of being infected such as from the introduction of a foreign agent such as serum, vaccine, antigenic substance or organism. "The transcriptome data show over-expression of complement component 1 (C1S), an anti-thrombin peptide (SERPINC1), and fibrinogen beta chain (FGB) during virulent infection." (PMID 19216742, 2009). "After infection, the expression of FGB was increased on the lung and both sides of the serosa." (PMID 36034702, 2022). "Results showed that MUC5AC, FGB, and CLDN18 were highly expressed only in the control group and L3 infection group, while CCL19 exhibited higher expression levels in the infection groups." (PMID 40979361, 2025). "ELISA assay confirmed the elevation of FGB and FGG in OBI samples, suggesting their potential as biomarkers for distinguishing OBI from HBsAg-positive infection." (PMID 39600945, 2024).
cancer (6 papers, 2018 to 2024). A tumor composed of atypical neoplastic, often pleomorphic cells that invade other tissues. "Fibrinogen is a protein that is encoded by three different genes (FGA, FGB, FGG), two of which were upregulated in plasma samples from cancer patients in the current study." (PMID 39146279, 2024). "By a targeted comparative proteomics, we succeeded in revealing an in situ differential expression of both the entire and the cleaved FGB forms in GC tissues, depending on cancer development, location, as well as pathological stage." (PMID 29518939, 2018). "FGB is a glycoprotein that is involved in blood clotting, and Hippo/YAP1, a regulator of cellular processes including proliferation, apoptosis, and differentiation, have both been implicated in cancer development and progression." (PMID 37953225, 2023). "Our work allowed to evidence a differential accumulation of FGB in gastric tissues of GC patients depending on the anatomical site affected by cancer: the entire FGB was found to be more abundant in the antrum of the stomach, while its cleaved forms showed a higher content in the corpus." (PMID 29518939, 2018). "When performing pairwise comparisons among the different stages of cancer, stage IV patients had increased expression of FGA, FGB, PERP, GPR107, CDH3 compared to controls." (PMID 39146279, 2024). "APOC3, APOH, HPX, and FGB expression levels were highest in HCC and were greater in normal tissues than that in cancer tissues." (PMID 35449866, 2022). "The expression levels of APOC3, APOH, HPX, and FGB were the highest in HCC and were higher in normal tissues than in cancer tissues." (PMID 35449866, 2022).
cardiovascular disease (3 papers, 2019 to 2022). "In addition, FGB is involved in other disease processes, such as wound healing, liver injury, allergic airway disease, cardiovascular disease, and microbial pathogenesis by modulating the host immune system." (PMID 33804769, 2021).
infectious disease (1 paper, 2022). A disorder directly resulting from the presence and activity of a microbial, viral, or parasitic agent in humans. "Interestingly, hub genes from age groups of 0-20 years old and 71-100 years old, namely, ARPC2, UBB, FGB, and FGG, are mostly involved in infectious diseases and the immune system." (PMID 36084955, 2022).
myopathy (1 paper, 2015). A disease of the muscle in which the muscle fibers do not function properly. "Birds suffering from this myopathy exhibit down-regulation of eight hemostatic genes (A2M, FGA, FGB, FGG, KNG1, SERPINC1 and VWF) and up-regulation of four other coagulation genes (F5, F10, PROS1 and F2R)." (PMID 26445145, 2015).
FGB also shares sentences with these, for which no sentence is quoted: Alzheimer disease (2 papers); cervical carcinoma (2); glaucoma (2); hemorrhage (2); Hypercholesterolemia (2); Parkinson disease 7 (2); thromboses (2); acute coronary syndrome (1); adenoma (1); age (1); amyloidosis (1); anemia (1); Arrhythmia (1); atrioventricular septal defect (1); babesiosis (1); bladder tumor (1); cataract (1); Cerebral ischemia (1); congenital hypothyroidism (1); cystic fibrosis (1); dementia (1); Disseminated intravascular coagulation (1); endocarditis (1); esophageal cancer (1); essential hypertension (1); gastric adenocarcinoma (1); hypertriglyceridemia (1); hypoalphalipoproteinemia (1); insuline resistance (1); intracranial hemorrhage (1).
A further 13 diseases each share a sentence with FGB in 1 paper.